CRB1 (crumbs cell polarity complex component 1)
Diseases named in the same sentence as CRB1 in open-access papers (continued):
Sharing a sentence is not in itself a finding about the gene and the disease.
retinal dystrophies (59 papers, 2008 to 2025). "This study was a retrospective case series of 14 patients from 11 families with molecularly confirmed CRB1-associated retinal dystrophy, each possessing at least one p.(Pro836Thr) variant." (PMID 40590804, 2025). "Collectively, our findings provide new insights into the genotype–phenotype correlations in CRB1-related retinal dystrophies and suggest that disease severity is linked to the impact of mutations on the isoforms expression." (PMID 41373703, 2025). "Mutations in the CRB1 gene have been reported in some cases, linking PPRCA to a wider spectrum of CRB1-associated retinal dystrophies." (PMID 41328152, 2025). "Pathogenic variants in CRB1 are responsible for several types of retinal dystrophies leading to a broad range of clinical manifestations." (PMID 41373703, 2025). "More than 450 variants have been linked to CRB1-associated retinal dystrophies, with the majority clustering in exons 7 (27%) and 9 (41%), which encode the second and the third laminin AG-like domains." (PMID 40590804, 2025). "Collectively, our data elucidate previously undescribed expression patterns of CRB1 isoforms during retinal cell differentiation and highlight key aspects of CRB1-associated inherited retinal dystrophies." (PMID 41373703, 2025). "X‐linked RS is clinically characterised by splitting of the macula and peripheral retina, whereas mutations in the CRB1 gene are usually associated with severe retinal dystrophies exhibiting variable phenotypes." (PMID 39676705, 2024). "The purpose of this study was to investigate the genotypic and phenotypic characteristics of CRB1-associated early onset retinal dystrophy (CRB1-eoRD) and retinal architecture by swept-source optical coherence tomography (SS-OCT)." (PMID 38466290, 2024). "It was later found that mutations in Crumbs homolog-1 (CRB1), a human homolog of the Drosophila protein Crumbs, caused retinal dystrophies in humans." (PMID 38790254, 2024). "We demonstrate that CRB1 is the most frequently mutated gene in pediatric retinal dystrophies in Chile, and we disclose a high degree of inbreeding in affected families, which results in a very limited number of mutations." (PMID 38892339, 2024). "Overall, a total of 6 patients (12 eyes) affected by a genetically confirmed CRB1-associated retinal dystrophy were recruited, with ages ranging between 10 and 67 years (mean age 36.4 ± 25.7 years) and a mean BCVA of 0.4 ± 0.25 logMAR." (PMID 36769743, 2023). "Mutations in the Crumbs homolog 1 (CRB1) gene cause severe and disabling inherited retinal dystrophies (IRDs)." (PMID 36830922, 2023). "It remains to be determined what controls CRB1 protein expression, localization, and turnover rate at the OLM to determine the progression of retinal degeneration in CRB1-associated retinal dystrophy phenotypes in CRB1 patients." (PMID 37541258, 2023). "In essence, our study highlights that CRB1-associated retinal dystrophy is characterized by vascular alterations on OCTA both in the macula and peripapillary region." (PMID 36769743, 2023). "Mutations in the Crumbs homolog 1 (CRB1) gene lead to severe inherited retinal dystrophies (IRDs), accounting for nearly 80,000 cases worldwide." (PMID 36830922, 2023). "In the present study, we describe OCTA findings in six patients affected by genetically confirmed CRB1-associated retinal dystrophy." (PMID 36769743, 2023). "It is still challenging to predict the progression of the spectrum of CRB1-associated retinal dystrophy phenotypes in CRB1 patients based on the genotype variants." (PMID 37541258, 2023). "This is interesting because CRB1-associated retinal dystrophies also involve inflammation and vascular leaks." (PMID 37691820, 2023). "Aim of the study: To report optical coherence tomography angiography (OCTA) findings in patients affected by CRB1-associated retinal dystrophies." (PMID 36769743, 2023).
retinal dystrophies (continued). "Altogether, these data provide essential information for future gene therapy approaches for patients with CRB1-associated retinal dystrophies." (PMID 37886604, 2023). "The successful use of mouse models to identify genetic modifiers of human diseases extends to models of eye diseases, including CRB1-associated retinal dystrophy." (PMID 35675330, 2022). "In humans, CRB1 and CRB2 contain 13 and 8 O-glycosylation sites, respectively, and mutations produce RP12 and other retinal dystrophies." (PMID 34001227, 2021). "Mutations in the Crumbs homolog 1 (CRB1) gene is a frequent cause of these retinal dystrophies in humans." (PMID 33808129, 2021). "In humans, mutations in the crb1 gene, mostly in the region encoding the extracellular domain, causes inherited retinal dystrophies." (PMID 31002663, 2019). "CRB1-linked retinal dystrophies represent a diverse spectrum and present with a wide complexity of clinical features." (PMID 28424578, 2017). "Four novel mutations and one reported mutation in the crumbs homolog 1 (CRB1) gene, which has been known to cause severe retinal dystrophies, were identified." (PMID 27670293, 2016). "CRB1 mutations are the second most common gene mutations found among LCA patients, accounting for 7.4–10 % of all LCA patients, and mutations in the CRB1 gene are associated with variable phenotypes of severe retinal dystrophies, ranging from LCA to RP." (PMID 26872607, 2016). "CRB1 gene mutations are associated with remarkable retinal findings in patients with retinitis pigmentosa and other fundus dystrophies." (PMID 26872607, 2016). "Mutations in CRB1 lead to a spectrum of autosomal recessive retinal dystrophies with variable phenotypes suggesting the influence of modifying factors." (PMID 25147295, 2015). "To date, more than 70 missense/nonsense mutations have been identified in CRB1 in patients with retinal dystrophies, and 19 variants have been reported associated with RP12 (HGMD)." (PMID 23592920, 2013). "These preclinical studies provide preliminary evidence that CRB2 gene therapy might have the potential to improve retinal function and morphology in CRB1-associated retinal dystrophy." (PMID 40590804, 2025). "Interestingly, although LCA is the most commonly reported phenotype for CRB1-associated retinal dystrophy (43%) and CRB1 is implicated in 7% to 17% of autosomal recessive LCA cases, none of the patients in our cohort exhibited this phenotype." (PMID 40590804, 2025). "Retinal dystrophies associated with CRB1 mutations may have preservation of the para-arteriolar retinal pigment epithelium (PPRPE) and retinal telangiectasia with exudation (also referred to as Coats-like vasculopathy)." (PMID 40416256, 2025). "Mutations in CRB1 often lead to a wide spectrum of retinal dystrophies, such as retinitis pigmentosa type 12 (RP12), Leber congenital amaurosis type 8 (LCA8), pigmented paravenous chorioretinal atrophy, and retinitis pigmentosa with coat’s-like exudative vasculopathy." (PMID 38802833, 2024). "CRB1-associated retinal dystrophies (CRB1-RDs) encompass a wide range of phenotypes, including LCA/EOSRD, RP, and MD, which may present as poor vision, nystagmus, hyperopia, and night blindness." (PMID 38466290, 2024). "Retinal dystrophy caused by a single CRB1 mutation is often limited to one quadrant of the retina." (PMID 38802833, 2024). "Nevertheless, CRB1-associated retinal dystrophy is a rare condition." (PMID 36769743, 2023). "CRB1 mutations cause variable severe retinal dystrophies with photoreceptor degeneration." (PMID 37691820, 2023). "Multicenter studies with a longitudinal follow-up should be designed to collect a high number of patients affected by CRB1-associated retinal dystrophy to ascertain the natural history evolution, investigating the correlation between dystrophy severity and vascular damage." (PMID 36769743, 2023).
retinal dystrophies (continued). "In fact, some scholars observed salt-and-pepper retinal dystrophy in younger patients and subsequently massive spicular and not nummular pigmentation at the posterior pole, which was reported to be a phenotypic feature of carriers of CRB1 variants." (PMID 36115989, 2022). "The CRB1 gene is associated with some inherited retinal dystrophies (IRD)." (PMID 28819299, 2017). "Mutations in the CRB1 gene are one of the at least 17 known gene mutations that are accused to cause LCA, and CRB1 mutations are associated with variable phenotypes of severe retinal dystrophies, ranging from LCA to rod-cone dystrophy [also called retinitis pigmentosa (RP)]." (PMID 26872607, 2016). "There have been reports that patients with bilateral Coats-like disease changes may have an underlying systemic or hereditary disease process, such as FSHD, incontinentia pigmenti, CRB1-associated retinal dystrophy, or familial exudative vitreoretinopathy." (PMID 25861398, 2015). "We suspect that in the pathological settings of AMD, retinal dystrophies and human diseases involving different CRB1 mutations (for example, Lebers congenital amaurosis, and childhood-onset dystrophies), the level of activation of subretinal MG/MΦ increases significantly." (PMID 25588310, 2015). "Mutations in the human CRB1 or CRB2 gene may lead to a broad spectrum of retinal dystrophies." (PMID 38802833, 2024). "Our finding that mutations in murine Arhgef12 and Prkci modulate Crb1rd8 retinal phenotypes to differing extents and with different lesion characteristics further supports the hypothesis that modifier gene variants contribute to clinical variability in CRB1-associated retinal dystrophy." (PMID 35675330, 2022). "Mutations in the CRB1 gene are associated with variable phenotypes of severe retinal dystrophies, and retinal dystrophies resulting from CRB1 mutations may be accompanied by specific fundus features such as coat’s like vasculopathy in retinitis pigmentosa patients." (PMID 26872607, 2016). "Indeed at the commencement of this study we had the further complication of discovering that these mice had a pre-existing retinal dystrophy due to the presence of the rd8 mutation in the crb1 gene and that the CD11c-eYFP+ cells in the retina represented activated microglia." (PMID 25623142, 2015). "This study of CRB1-related retinal dystrophy reports detailed phenotyping of patients molecularly confirmed to have the p.(Pro836Thr) variant and characterizes their key clinical and electrophysiological features." (PMID 40590804, 2025). "CRB1 mutations are associated with different IRDs ranging from milder forms of RCD and CRD to more severe forms such LCA and as early onset retinal dystrophy." (PMID 38622537, 2024). "Biallelic mutations of the CRB1 (crumbs cell polarity complex component 1) gene (MIM: 604,210) are a rare cause of inherited retinal dystrophies (IRDs)." (PMID 38622537, 2024). "Disease symmetry and reasonable window for intervention highlight CRB1 retinal dystrophies as a promising target for trials of novel therapeutics." (PMID 36099972, 2023). "Studies have reported that USH2A, EYS and CRB1 are the top three genes responsible for inherited retinal dystrophy." (PMID 34977041, 2021). "Altogether, this indicates the potential use of AAV-mediated gene therapy for CRB1-related retinal dystrophies." (PMID 33808129, 2021). "Several genes have been shown to be involved in early onset retinal dystrophies, including CRB1 and RPE65." (PMID 32922261, 2020). "Mouse CRB2 acts as the modifying factor of CRB1-related retinal dystrophies, since reduction or full ablation of CRB2 in combination with loss of CRB1 results in an exacerbation of the retinal phenotype observed in Crb1 knockout retinas." (PMID 31438467, 2019). "A previous study showed that USH2A, EYS, and CRB1 were the top three genes contributing to inherited retinal dystrophy in Chinese patients." (PMID 31269016, 2019).
retinal dystrophies (continued). "The retinal appearance, while atypical for patients with known Stargardt Disease, is similar to that seen in retinal dystrophies attributable to CRB1." (PMID 22863181, 2012). "This study aimed to describe the OCTA features in eyes affected by CRB1-associated retinal dystrophies, as no prior study has explored the vascular alterations in these disorders." (PMID 36769743, 2023). "Some of these proteins are well-studied in retinal dystrophy, such as CRB1, RP2, RPE65, and PCDH15." (PMID 36139394, 2022). "Translational studies using these Crb1rd8 modifier mouse models, which are readily available to researchers, may yield insights that improve the care of patients affected by CRB1-dependent retinal dystrophy." (PMID 35675330, 2022). "Loss of either CRB1 or CRB2 in MGCs results in mild retinal dystrophy, without impairing retinal function." (PMID 31438467, 2019). "On the other hand, it is interesting that, while lack of function of CRB1 in human retina causes retinal dystrophies, this same mutation does not cause any apparent brain dysfunction or manifest functional alteration." (PMID 30076417, 2018). "CRB1 is one of many genes analyzed in molecular diagnosis for inherited retinal dystrophy." (PMID 28819299, 2017). "Therefore, it could be a potential option for the genome editing gene therapy of retinal dystrophies related to CRB1." (PMID 38790254, 2024). "Furthermore, the detailed characterization of CRB1 macular OCT features will likely be helpful toward its inclusion among the inherited retinal dystrophy genotypes that are currently used to train and validate deep learning systems for automated diagnosis and classification." (PMID 36099972, 2023). "Of these patients, seven had monoallelic pathogenic variants in ABCA4, one had biallelic variants of uncertain significance (VUS) in ABCA4, two had monoallelic VUS in ABCA4, and eight harbored VUS in other retinal dystrophy-related genes, including KCNV2, RIMS1, CRB1, CFH, RP1L1, UNC119, and SEMA4A." (PMID 41234456, 2025). "Several rodent models lacking one or both CRB1/CRB2 homologs present retinal dystrophy of different severities, indicating the functional redundancy and complex gene modifying system among CRB proteins." (PMID 38802833, 2024). "Currently, there is no treatment available for CRB1-related retinal dystrophies." (PMID 33808129, 2021). "Crb1KOCrb2ΔimmPRC retinas lacking CRB1 and CRB2 from immature photoreceptors showed retinal dystrophy by fusion of the inner and outer nuclear layer throughout the retina." (PMID 31438467, 2019). "As no genotype-phenotype correlation in CRB1 retinal dystrophies has been identified, additional down-regulation of CRB2 function in human CRB1-mutant retinas might range from CRB1-retinitis pigmentosa to CRB1-LCA." (PMID 24339791, 2013).
retinitis pigmentosa (57 papers, 2010 to 2025). Retinitis pigmentosa (RP) is an inherited retinal dystrophy leading to progressive loss of the photoreceptors and retinal pigment epithelium and resulting in blindness usually after several decades. "Basically, there is only one IRD phenotype that can be associated with a specific gene: retinitis pigmentosa with preserved para-arterial pigment epithelium (RP12) is associated with the CRB1 gene." (PMID 39963372, 2025). "Less common phenotypes associated with CRB1 mutations include Coat’s-like vasculopathy (also known as Coat’s-like retinitis pigmentosa), keratoconus, and nanophthalmos." (PMID 41373703, 2025). "This group also included three exhibiting specific phenotypes strongly associated with CRB1 mutations, such as retinitis pigmentosa with preserved para-arteriolar retinal pigment epithelium (PPRPE)." (PMID 41373703, 2025). "We generated human induced pluripotent stem cell (iPSC)-derived retinal organoids of patients with retinitis pigmentosa caused by biallelic CRB1 mutations and evaluated them against autologous gene-corrected hiPSCs and hiPSCs from healthy individuals." (PMID 37541258, 2023). "In this study, we present a novel Müller cell-specific Crb1KOCrb2LowMGC retinitis pigmentosa mouse model (complete loss of CRB1 and reduced levels of CRB2 specifically in Müller cells)." (PMID 33575434, 2021). "CRB1 mutations led to retinitis pigmentosa 12, LCA8, or childhood- and juvenile-onset cone–rod dystrophy." (PMID 35118070, 2021). "In this study, we identified mutations in CRB1 in the Chinese and Indian populations with the autosomal recessive retinitis pigmentosa using the whole exome sequencing technology." (PMID 27670293, 2016). "In conclusion, our present study reveals five mutations in CRB1 gene in Chinese and Indian populations with retinitis pigmentosa by the whole exome sequencing." (PMID 27670293, 2016). "The p.R764C mutation in CRB1 was previously reported in retinitis pigmentasa 12 in the Caucasian population in 199913, our result confirmed that this mutation caused recessive retinitis pigmentosa in the Indian population." (PMID 27670293, 2016). "In the previous report, the missense mutation p.R764C was revealed in retinitis pigmentosa 12, which introduces a substitution of Arginine to Cystine at the 764 amino acid of the CRB1 protein and was predicted probably to be damaging to the protein function." (PMID 27670293, 2016). "Mutations in human CRB1 cause retinitis pigmentosa (RP), while Crb1 knockout mice show more limited retinal defects." (PMID 25661870, 2015). "Mutations in CRB1 cause retinitis pigmentosa and crb genes were known to play key roles in apical differentiation." (PMID 25144710, 2014). "In contrast, Crb2 cKO mice display a severe phenotype with progressive loss of photoreceptors and retinal activity mimicking CRB1-related retinitis pigmentosa." (PMID 24339791, 2013). "Therefore, CRB1 gene variants often lead to a variety of retinal dystopathies, including retinitis pigmentosa (RP), LCA, and macular dystrophy." (PMID 36115989, 2022). "Recently, we showed that conditional deletion of mouse Crb2 in the retina results in early retinal disorganization leading to severe and progressive retinal degeneration with concomitant visual loss that mimics retinitis pigmentosa due to mutations in the CRB1 gene." (PMID 24324803, 2013). "Furthermore, mutations in CRB1 causes retinal diseases including retinitis pigmentosa 12 and Leber Congenital Amaurosis in humans." (PMID 20209135, 2010). "All participants had a formal diagnosis of an inherited retinal disease (n = 3 Usher syndrome, n = 1 CRB1-related retinitis pigmentosa, n = 1 choroideremia, n = 1 Stargardt disease) or a structural eye abnormality (n = 1 microphthalmia)." (PMID 38188864, 2024).